XBP1 (X-box binding protein 1)
Diseases named in the same sentence as XBP1 in open-access papers (continued):
Sharing a sentence is not in itself a finding about the gene and the disease.
breast carcinoma (continued). "Abundant research has accumulated compelling evidence affirming that therapeutic interventions targeting PERK, GRP78, and IRE1/XBP1 have substantial potential to enhance the effectiveness of breast cancer treatment." (PMID 38468244, 2024). "Endocrine-resistant breast cancers have elevated expression of XBP1, where it drives endocrine resistance by controlling the expression of its target genes." (PMID 36997866, 2023). "The targeting of XBP1 has been considered a promising therapeutic approach to overcome endocrine resistance in breast cancer." (PMID 38203358, 2023). "Our results showing the increased expression of RRM2, CDC6 and TOP2A in XBP1-dependent manner provides a mechanism for their overexpression in breast cancers." (PMID 36997866, 2023). "Next, the expression of XBP1 mRNA was analysed in a panel of 50 breast cancer cell lines [luminal (n = 13), HER2-enriched (n = 16), basal-like (n = 21)] grouped according to molecular subtypes." (PMID 36997866, 2023). "Further analysis of XBP1 expression in molecular subtypes of breast cancer showed highest expression in luminal subtype as compared to basal or HER2-enriched subtypes (SF 3A-B)." (PMID 36997866, 2023). "While XBP1 is primarily known for its role in EnR stress and protein folding, emerging evidence suggests its involvement in the development and progression of breast cancer." (PMID 38203358, 2023). "The transcriptional activity of spliced XBP1 (XBP1s) is a major component of its biological effects, but the targets of XBP1s in estrogen receptor (ER)-positive breast cancer are not well understood." (PMID 38203358, 2023). "Taken together, these analyses indicate increased expression of XBP1 in ER-positive and/or luminal subtype of breast cancer." (PMID 36997866, 2023). "Multi-omics analysis of primary breast tumour samples of TCGA cohort has shown that one of the salient feature of ER-positive breast cancers is increased expression of ER and XBP1 at mRNA and protein level." (PMID 36997866, 2023). "Using web-based analysis of several breast cancer cohorts, we confirmed higher expression of XBP1 in ER-positive/luminal breast cancer." (PMID 36997866, 2023). "In agreement with results in breast cancer tissue, cell lines also showed highest expression of XBP1 in luminal subtype (SF 3C)." (PMID 36997866, 2023). "In fact, in human biopsies of breast cancer, lymphoma, or multiple myeloma, x-box-binding protein-1 (XBP-1), a protein that signals the activation of the UPR complex, was highly expressed and correlated with poor prognosis." (PMID 36901921, 2023). "We determined association of XBP1-gene signature (RRM2, CDC6 and TOP2A) with the outcome in breast cancer." (PMID 36997866, 2023). "Correlation between XBP1 spliced/unspliced ratio and clinicopathological parameters of breast cancer patients." (PMID 37706018, 2023). "The high XBP1 expression in metastatic cancer cells from PL6 indicates a relationship between XBP1 expression and Luminal B breast cancer metastasis." (PMID 36148946, 2022). "Further, several studies investigated the therapeutic potentials of targeting Xbp1 and showed that aptamer-conjugated Xbp1 siRNA nanoparticles or scAAV2 vectors encoding the Xbp1 siRNAs could efficiently impair angiogenesis and suppress tumor growth in breast cancer." (PMID 36348288, 2022). "Stratifying breast cancer samples by BiP mRNA and protein enriched for known functional effects of BiP on proteostasis including activation of the IRE1alpha/XBP-1 UPR arm." (PMID 36547124, 2022). "NFkB has been shown to be an important regulator of XBP-1 expression in breast cancer cell lines, linking NFkB activity with the XBP-1 pathway." (PMID 35663979, 2022). "The IRE1α/XBP1 pathway was shown to promote breast cancer progression and tumor initiation by activating the hypoxia pathway governed by HIF-1α." (PMID 35349489, 2022).
breast carcinoma (continued). "XBP1 is considered as a biomarker of poor clinical outcomes in patients with pulmonary adenocarcinoma, breast cancers, and multiple myeloma." (PMID 35222510, 2021). "In contrast, the knockdown of XBP1 restored expression of E-cadherin and cell-cell junction formation, inhibiting breast cancer cell invasion and tumor formation." (PMID 33746610, 2021). "We further analyzed the relevance of CCDC170, IRE1 and XBP1 expression to breast cancer prognosis in two independent cohorts (TCGA and GEO), and found that higher expression of CCDC170, IRE1 and XBP1 correlated with better OS in GEO." (PMID 33291081, 2020). "XBP1 expression is upregulated in breast cancer, oral cancer, colorectal cancer, lung cancer, hepatocellular cancer, osteosarcoma, and esophageal cancer tissues, compared with matched non-tumor tissues." (PMID 32793479, 2020). "Previous studies reported that XBP1 was overexpressed in various human cancer types, such as breast cancer, oral cancer, lung cancer, colorectal cancer, and hepatocellular cancer." (PMID 32793479, 2020). "It is responsible for alternative splicing of the XBP1 transcription which induces Snail expression to promote EMT in breast cancer cells." (PMID 33028359, 2020). "In order to test the XBP1 biochip in a physiologically relevant model, basal XBP1 levels were assessed in several breast cancer cell lines of different subtypes." (PMID 31807121, 2019). "At the protein level this ratio-based measurement of XBP1 isoform expression was suitable (though statistically less powerful) in the breast cancer models where XBP1u reported at low levels with little variation." (PMID 31807121, 2019). "Application of this biochip to detect XBP1 splicing at the protein level in relevant breast cancer models, under basal conditions as well as pharmacological inhibition and paclitaxel induction, confirmed the findings of previous studies." (PMID 31807121, 2019). "In the ChIP assay, XBP1 directly binds to the promoter of its host gene IA-2 to induce miR-153 expression in breast cancer cells under hypoxia." (PMID 31795469, 2019). "The XBP1 gene had an important role in the tumorigenicity in breast cancer subtypes and had higher expression level and activity in TNBC than luminal." (PMID 30866472, 2019). "It has been demonstrated that an increased level of spliced XBP1 relatively to unspliced XBP1 correlates with poor prognosis in breast cancer, and XBP1 has been proposed as a therapeutic target for solid tumors." (PMID 31216687, 2019). "Recent studies have shown constitutive activation of IRE1α and resultant XBP1 splicing in basal-like (when stratified molecularly) and triple negative (when stratified by receptor expression) breast cancers." (PMID 31807121, 2019). "In support of this conclusion, a human luminal breast cancer cell line overexpressing either XBP1s or an unsplicable XBP1 mutant produced faster growing tumours when injected into mice compared to wildtype cells." (PMID 30248920, 2018). "Similar to the results obtained in the breast cancer cell lines, the ratio of spliced to total XBP1 was highest in samples derived from basal-like breast cancers (most of which are TNBC) compared to luminal samples, and tumor-associated normal tissue (TAN)." (PMID 30111846, 2018). "Clinical trials have further demonstrated that XBP1 expression levels are highly correlated to cell survival in ER+ breast cancer patients." (PMID 30159133, 2018). "A comprehensive study of gene expression signatures in primary samples revealed an overexpression of XBP1 in luminal breast cancer, where it is co-expressed with ESR1." (PMID 30248920, 2018). "MALAT1 promotes proliferation and invasion abilities of breast cancer cells through XBP1 (X-box binding protein 1)-HIF (hypoxia-inducible factor)-1α pathway in MDA-MB-231 and through Her-2 pathway in MDA-MD-435." (PMID 29416769, 2018).
breast carcinoma (continued). "In fact, the regulation of IRE1/XBP-1 increased drug sensitivity and decreased cell proliferation in breast cancer-derived cell lines and in mice models." (PMID 30134550, 2018). "XBP1 is also known to modulate endoplasmic reticulum lipid raft associated 2 (ERLIN2) protein expression, which possess the capacity to protect breast cancer cells from ERAD promoting their survival." (PMID 30159133, 2018). "Examples of these disparate functions include the fact that high levels of Xbp1 are present in some breast cancer tissues, and a greater amount of the spliced XBP1-message correlates with poor prognosis in TNBCs." (PMID 29145850, 2017). "Anti-estrogen-resistant breast cancer cell lines express elevated levels of BiP and Xbp1, suggesting that UPR induction contributes to therapy resistance." (PMID 29145850, 2017). "Concerning breast cancer, a recent report has shown that XBP1 is activated in triple-negative breast cancer." (PMID 28332555, 2017). "Recent research further shows that XBP1 is a coregulator of HIF1α and controls the HIF1α transcriptional program in breast cancer." (PMID 27133203, 2016). "XBP1 has been demonstrated in the setting of breast cancer, to be an estrogen-regulated gene strongly correlated with estrogen receptor alpha (ERα) expression." (PMID 27668268, 2015). "In human breast cancer patients, XBP1 mRNA levels correlate with tamoxifen responsiveness, further supporting the role of XBP1 in endocrine therapy resistance." (PMID 26157705, 2015). "CA1 plays important roles in the calcification, apoptosis and migration of tumour cells and contributes to breast cancer tumourigenesis by regulating the expression of AR and XBP1." (PMID 26459317, 2015). "In breast cancer, XBP1 was activated and correlated with poor prognosis in triple-negative breast cancer patients." (PMID 26633383, 2015). "Previous studies showed that XBP1 was overexpressed and correlated with clinical progress in multiple cancers, including the myeloma and breast cancer." (PMID 26633383, 2015). "Targeting XBP1 through RNAi restored endocrine therapy sensitivity in resistant breast cancer cell lines." (PMID 26157705, 2015). "In previous studies, activation of XBP1 was reported and correlated with clinical outcome in breast cancer." (PMID 26633383, 2015). "We specifically investigated the effect of lenalidomide on XBP1-specific memory CD8+ CTL against breast cancer, colon cancer and pancreatic cancer cells, which overexpress XBP1 unspliced and spliced antigens." (PMID 27668268, 2015). "Previous studies have demonstrated that XBP1 expression is increased in estrogen therapy resistant breast cancer cell lines and is co-expressed with the estrogen receptor alpha (ERalpha) in breast tumors." (PMID 26517687, 2015). "ER-β activation was shown to inhibit IRE1, thereby reducing XBP1 splicing in breast cancer cell lines." (PMID 26157705, 2015). "The activities of different memory cell subsets were specifically enhanced after lenalidomide treatment in XBP1-CTL (n=3) against breast cancer (MDA-MB231), pancreatic cancer (Panc1) and colon cancer (SW480) cells." (PMID 27668268, 2015). "Overexpression of XBP1 increased snail protein, reduced e-cadherin levels, and increased mesenchymal markers in breast cancer cells." (PMID 26157705, 2015). "XBP1 expression is widely reported in all breast cancer subtypes and correlates with poor prognosis." (PMID 26157705, 2015). "Expression of XBP1 with that of ERα suggests that XBP1 plays an important role in driving this subtype of breast cancer." (PMID 26157705, 2015). "XBP1 increased expression and splicing have been found in hepatocellular carcinoma and breast cancer." (PMID 26491226, 2015). "XBP1 splicing to XBP1(s) by IRE1α promotes cell survival in breast cancer cells, and thus, protein levels of XBP1(s) was determined." (PMID 25339305, 2014).
breast carcinoma (continued). "STAT1-/- ERα+ mammary tumors also showed elevated transcription of genes characteristic of luminal breast cancers (for example, keratin 8, keratin 18, XBP1, GATA3, MYB, AREG, and FOXA1)." (PMID 22264274, 2012). "Of particular interest in this study, we found that the UPR pathway modulated ERLIN2 protein expression in breast cancer cells through the IRE1α/XBP1 axis." (PMID 22681620, 2012). "The IRE1α/XBP1 axis in the ER stress pathway modulated expression of ERLIN2 protein levels in breast cancer cells." (PMID 22681620, 2012). "The UPR-activated splice variant of XBP-1, (XBP-1s), confers anti-oestrogen resistance and oestrogen-independent growth in breast cancer cell lines in vitro." (PMID 19861963, 2009). "Expression of GRP78 and XBP-1 was demonstrated in 76% and 90% of the breast cancers, respectively, and correlated with oestrogen receptor positivity (P=0.045 and 0.017, respectively)." (PMID 19861963, 2009). "In view of this, our data relate to previous findings by demonstrating that derlin-1, one part of the ERAD machinery and an effecter downstream of XBP-1, is frequently overexpressed in breast cancer." (PMID 18205950, 2008). "In this study, we demonstrated significantly elevated levels of XBP1 and XBP1s in HR+/HER2− breast cancer, which were associated with an unfavorable therapeutic response and poor prognosis in patients who received the combination treatment of CDK4/6 inhibitors plus endocrine therapy." (PMID 40940685, 2025). "Furthermore, FOXA1 and XBP1 genes have been identified as key biomarkers across all breast cancer subtypes except Basal-like subtype." (PMID 40468582, 2025). "Additionally, in breast cancer, the IRE1α-XBP1 signaling pathway can activate the transcription of downstream Snail genes, enhancing the migratory and invasive capabilities of breast cancer cells." (PMID 40745648, 2025). "Moreover, Myc in breast cancer enhances IRE1α transcriptional activity by forming a complex with XBP1." (PMID 38509524, 2024). "XBP1 recognition by the NPs impaired angiogenesis and inhibited cell proliferation, suppressing breast cancer growth effectively, and sensitizing chemotherapy in a breast cancer mouse model." (PMID 39199788, 2024). "The overexpression of XBP1 has been observed in various human cancers, including breast cancer." (PMID 38468244, 2024). "Finally, Immunohistochemistry (IHC) and immunoblotting were used to investigate XBP1 expression in HER2-positive breast cancer tissues." (PMID 39006091, 2024). "Genetic evidence of XBP1 in AF and breast cancer provides new ideas for the treatment of both, but a large number of studies are still needed to validate the feasibility and safety of drug-targeted inhibition of XBP1 in the combined state of the two diseases." (PMID 39170695, 2024). "Furthermore, tamoxifen, another major anti-tumor drug for treating breast cancer, can also increase XBP1 mRNA expression in drug-resistant breast cancer cells." (PMID 35269888, 2022). "X-box binding protein 1 (XBP1) is mainly expressed in breast cancer (BC) in human cancers." (PMID 35543228, 2022). "c-Myc has been shown to activate the IRE1α/XBP1 pathway in breast cancer cells." (PMID 35453482, 2022). "Finally, we aimed at validating the expression of XBP‐1 according to ERα status and age in human breast cancer." (PMID 36111352, 2022). "In breast cancer, XBP1 has been identified as a novel regulator of EMT and cancer progression." (PMID 33746610, 2021). "XBP1 deletion by RNA NPs impaired angiogenesis and dramatically suppressed breast cancer." (PMID 33413427, 2021). "Our recent results show XBP1 is involved in HER2 + breast cancer development and chemoresistance." (PMID 33413427, 2021). "The MDA-MB-231 breast cancer cell line was used as a positive control cell line because it displays highly efficient IRE1α activation and XBP1 mRNA splicing under ER stress 40, and glucose deprivation and hypoxia were set as the positive control conditions for ER stress." (PMID 33897873, 2021).
breast carcinoma (continued). "In epithelial malignant neoplasms such as esophageal squamous cell carcinoma and breast cancer, XBP-1 could promote malignant cell propagation via different signaling pathways." (PMID 32550011, 2020). "Notably, ESR1 and XBP1 are co-expressed in breast cancer tissues, and XBP1s can bind to the X-box in the ESR1 promoter, thus inducing its transcription." (PMID 33291081, 2020). "In addition, XBP1 had been reported to contribute to cancer progression with increased expression in many human cancers such as breast cancer, hepatocellular carcinoma, and pancreatic adenocarcinoma." (PMID 32586376, 2020). "Perhaps the high metastatic potential of this subtype of breast cancer could be related to a positive action of HIF1α-XBP1 on EMT, whose occurrence in TNBC is well established." (PMID 31071975, 2019). "Moreover, it has been reported that high levels of XBP1 suppressed an aggressive phenotype of breast cancer-derived stem cells." (PMID 30134550, 2018). "XBP1 promotes the growth of ESR1+ breast cancers by regulating ESR1 signaling." (PMID 30248920, 2018). "Given that some studies have already shown that XBP1(S) overexpression prevents cell cycle arrest in breast cancer cell lines, it was possible that XBP1 might play a part in cell cycle regulation." (PMID 28555054, 2017). "In breast cancer cell line models, depletion of XBP1 inhibited tumor growth and tumor relapse." (PMID 28245581, 2017). "For breast cancer, XBP1 promoted triple-negative breast cancer by regulating HIF-1α pathway." (PMID 26633383, 2015). "Our results showed that the frequency of T-bet expressing and IFN-γ producing XBP1-CTL was consistently higher in total CD3+CD8+ T cells after lenalidamide treatment, as compared to untreated XBP1-CTL in response to breast cancer (MDA-MB231), pancreatic cancer (Panc1) or colon cancer (SW480) cells." (PMID 27668268, 2015). "Reduction of XBP1 by ER-β is a novel mechanism by which ER-β inhibits breast cancer cell growth." (PMID 26157705, 2015). "Indeed, overexpression of XBP1 increases proliferation in breast cancer cells and prevents antiestrogen therapy-induced cell cycle arrest." (PMID 23335849, 2013). "Similarly, increases in spliced XBP1 relative to unspliced XBP1 have been shown to correlate with poor prognosis in breast cancer and XBP1 has been proposed as a therapeutic target for solid tumors." (PMID 22069719, 2011). "A previous study has demonstrated that XBP-1 is upregulated in human breast cancer." (PMID 18205950, 2008). "Furthermore, ATF6 has been shown to promote brain metastasis in breast cancer while XBP1 supports invasion and proliferation by inducing MMP9 (matrix metalloproteinase-9) expression and remodelling of the extracellular matrix in human esophageal squamous cell carcinoma." (PMID 41228282, 2025). "In addition, the XBP1 gene was found to be a common druggable target for AF and breast cancer." (PMID 39170695, 2024). "Collectively, our findings reveal a crucial role for the spliced XBP1-miR-378 pathway in ER-positive breast cancer and suggest that XBP1s may contribute to the development of endocrine-resistant breast cancer, in part, by downregulating the expression of miR-378." (PMID 38203358, 2023). "XBP1s in breast cancer cells has been shown to drive malignant progression by promoting tumor cell survival and metastasis under hypoxic conditions, and previously, we reported that aberrant IRE1α-XBP1 signaling in intratumoral leukocytes facilitated immune escape and metastasis in ovarian cancer." (PMID 36624093, 2023). "To determine whether XBP-1s directly binds to the TPP2 gene, we reviewed the ENCODE chromatin immunoprecipitation-sequencing (ChIP-seq) database and found that the TPP2 promoter displayed XBP-1 ChIP peaks in the breast cancer cell lines HS578T, MDA-MB-231, and T47D." (PMID 35794100, 2022).